HNF4A (hepatocyte nuclear factor 4 alpha)
Diseases named in the same sentence as HNF4A in open-access papers (continued):
Sharing a sentence is not in itself a finding about the gene and the disease.
liver cancer (continued). "Former studies indicated that miR-24 could reduce the FX and FXII mRNA levels by downregulating HNF-4α in liver cancer cell line HepG." (PMID 28694557, 2017). "For example, HNF4-α could represent a central regulator of gene transcription in hepatocytes, and a strong candidate to be involved in liver cancer cell development." (PMID 28415592, 2017). "As a concrete example, FOXA1 (HNF4A) is a transcription factor important for the specification of the intestine and stomach as well as liver and silencing of HNF4A leads to liver cancer." (PMID 27562343, 2016). "For instance, epigenetic silencing of HNF4A (a key liver-specifying TF) in liver cancer has been linked to loss of promoter H3K4me3 without changes in promoter methylation." (PMID 27562343, 2016). "Targeting of HNF4α by viral small non-coding RNA more closely links HCV infection to hepatocellular transformation, and raises the possibility of antisense RNA-based therapy of HCV infection-associated liver cancer." (PMID 26157476, 2015). "This protein plays an essential role in liver development, and its master regulatory role in the maintenance of the metabolic competence of the liver has stimulated research on HNF4α targeted cancer therapies for its ability to revert liver cancer to a less aggressive phenotype." (PMID 21829439, 2011). "Finally, HNF1A and HNF4A have been described to prevent EMT in liver cancer." (PMID 30909444, 2019). "Complicating the mechanistic understanding of HNF4α in liver cancer is the fact that there are two promoters (P1 and P2) that drive the expression of different HNF4a transcript variants, which are differentially expressed not just in human HCC, but also colon cancer." (PMID 30341289, 2018). "HNF4A could be a key factor connecting nicotine metabolism and liver cancer." (PMID 28583088, 2017). "To investigate whether hepatic Exo70 expression was regulated by HNF4α, the most important and abundant transcription factor in liver, we knocked down endogenous HNF4α in human hepatic cancer cell line Hep G2, and a dramatic decrease in the protein and mRNA expression level of Exo70 was observed." (PMID 26848864, 2016). "Furthermore, HNF4α was studied for its pivotal role in liver cancer." (PMID 25872475, 2015). "Thus, HNF4A is likely to be a novel driver gene for liver cancer, as well as ARID2 and RPS6KA3." (PMID 25526364, 2014). "Hepatocyte nuclear factor 4 alpha (HNF4A) and HIC ZBTB transcriptional repressor 1 (HIC ZBTB transcriptional repressor 1) in liver cancer HIC1) binds competitively to KAT2B, inhibiting the production of GSH and promoting ferroptosis." (PMID 40327848, 2025). "Our findings shed light on the regulatory mechanisms of liver cancer growth by KDM1A and HNF4A, highlighting their essential roles in liver-TE accessibility and transcriptional activity." (PMID 38965210, 2024). "In liver cancer, GSH production is regulated by hepatocyte nuclear factor 4 alpha (HNF4A) and the HIC ZBTB transcriptional repressor 1 (HIC1), which competitively binds to KAT2B." (PMID 39595619, 2024). "We identified YWHAE as significantly associated with liver fibrosis, AVIL, FIS1, MUC1, ACOT7, CLUH, HNF4A, and TNFSF10 with liver cancer, and AVIL with liver disease-related mortality (FDR-adjusted P values < 0.05)." (PMID 38862964, 2024). "HNF4α has been identified as suppressing ferroptosis, and HIC1 identified as stimulating ferroptosis in liver cancer." (PMID 36105219, 2022). "While HNF4α works to drive differentiation towards hepatic cellularity, PRMT5 antagonizes HNF4α expression assisting in liver cancer stem cell maintenance." (PMID 33768972, 2021). "Our findings suggest an intricate interplay between the genes CYP2D6, HNF4A, and IL6 in AS and CA liver cancer patients." (PMID 34597305, 2021). "Modification of the epigenetic status of liver cancer cell line HepG2 by 5-Azacytidine (5-AZA) and Vitamin C led to increased levels of HNF4α along with elevated drug metabolic capacity." (PMID 34771521, 2021).
liver cancer (continued). "Based on their mRNA expression levels of liver-specific markers, including HNF4α and its direct target HNF1, and mesenchymal markers, these liver cancer cell lines can be clustered into two groups (13 epithelial vs. 12 mesenchymal)." (PMID 32770044, 2020). "Our study identifies HNF4α-mediated SAA metabolism as a key mechanism of EMT suppression that contributes to nutritional and chemical sensitivity in liver cancer." (PMID 32770044, 2020). "In this study, we establish a link between hepatocyte nuclear factor 4α (HNF4α) and SAA metabolism in liver cancer." (PMID 32770044, 2020). "We examined the liver cancer stem cell or progenitor markers (AFP, CD133, EPCAM, and KRT19), and hepatocyte terminal differentiation markers (ALB, G6PC, CYP3A4, and HNF4A) in subgroup of patients with different SOX signature scores." (PMID 31462277, 2019). "RNA-Seq analysis observed a strong correlation between HNF4A expression and expression of its target genes, ApoB and HNF1A, in liver cancers." (PMID 29899848, 2018). "Importantly, forced expression of BMAL1 in HNF4α-positive liver cancer cells impairs spheroid growth in culture and tumor growth in vivo, demonstrating that manipulation of the circadian clock in HNF4α-positive HCC could be a realistic strategy to slow or reverse growth of human HCC." (PMID 30341289, 2018). "We previously reported the regulation of P2 promoter driven HNF4α isoforms in hepatocarcinogenesis and an identification of novel disease candidate genes found to be regulated in an EGF-induced mouse liver cancer model and human HCC." (PMID 25901575, 2015). "To explore the regulatory impact of liver-TEs on HNF4A expression, we utilized CRISPR/Cas9 technology to concurrently remove each cluster of TEs, situated either upstream or downstream of the P1-driven HNF4A TSS, referred to as HNF4A-liver-TEs, in liver cancer cells." (PMID 38965210, 2024). "Given the extensive role of HNF4α in basic metabolism in the liver, as well as liver cancer, it is not surprising that HNF4α has been found to interact with proteins that regulate the circadian clock and play an active role in the hepatic circadian clock." (PMID 37600688, 2023). "A knockout of HNF4α increases chemically induced liver cancer in rodents and P1-HNF4α interacts with cyclin D1 in a negative reciprocal regulatory axis to control hepatocyte proliferation." (PMID 37600688, 2023). "One transcription factor, HNF4A, identified as a ferroptosis suppressor mediates one category of genes called ferroptosis downregulated factors (FDF) by affecting the biosynthesis of glutathione in liver cancer." (PMID 37709486, 2023). "Increasing the concentration of GSH by targeting HNF4α and HIC1 might improve soferanib resistance for liver cancer treatment." (PMID 36105219, 2022). "In search for the underlying mechanism that may explain the disparity between AS and CA liver cancer patients, we have performed an IPA network analysis on the upstream regulator, HNF4A." (PMID 34597305, 2021). "The imbalance between the transcription factors HIC1 and HNF4A, regulating ferroptosis up-regulated factors (FUF), and ferroptosis down-regulated factors (FDF), respectively, may help treat liver cancer." (PMID 35047016, 2021). "In addition, HNF4α has been shown to re-differentiate HCC cells into hepatocytes and inhibits EMT, thereby blocking the occurrence of liver cancer, however, PRMT5 antagonizes the expression of HNF4α and helps maintain liver cancer stem cells." (PMID 34513846, 2021). "Collectively, our results suggest that the status of HNF4α and SAA metabolism may dictate the sensitivity of liver cancer cells to methionine/cystine restriction and sorafenib treatment." (PMID 32770044, 2020).
liver cancer (continued). "Through bioinformatic analyses, metabolomics, and molecular, cellular and in vivo characterizations, we demonstrate that HNF4α plays a central role in controlling hepatic SAA metabolism and dictating sensitivity to methionine restriction in liver cancer both in vivo and in vitro." (PMID 32770044, 2020). "Importantly, the positive correlation between HNF4α and SAA metabolic enzymes had functional consequences in liver cancer cells." (PMID 32770044, 2020). "Taken together, our observations indicate that HNF4α, SAA metabolism genes, and SAA metabolism are positively linked in human liver tumors and cell lines, and that SAA metabolism is altered in HNF4α-negative mesenchymal liver cancer cell lines." (PMID 32770044, 2020). "RT-PCR and Western blot analysis revealed that high levels of HNF4A mRNA and HNF4A protein expression were found in highly differentiated liver cancer cells but not in undifferentiated liver cancer cells, including HLE and HLF cells." (PMID 29899848, 2018). "Similarly, the exact role of the HNF4α isoforms in liver cancer is not completely clear." (PMID 37600688, 2023). "Interestingly, not all studies support the point that HNF4α inhibits liver cancer." (PMID 36249028, 2022). "The reason is, perhaps, that SMC treatment only led to slight elevation of HNF4α expression in normal primary hepatocytes, whose expression level is already fairly high, unlike in liver cancer cells, where SMC's induction could enhance the HNF4α expression much more significantly." (PMID 35343115, 2022). "Co-staining with hepatocyte marker (HNF4α) or cholangiocyte marker (CK19) revealed that a proportion of LGR5 cells in the tumor express HNF4α or CK19, suggesting that LGR5+ cells may give rise to both a HCC-like and a CC-like phenotype, the two main types of primary liver cancer." (PMID 32327656, 2020). "Although the expression of HNF4A was not significantly different between AS and CA liver cancer patients in our study, our IPA analysis did identify HNF4A as an upstream regulator of CYP2D6." (PMID 34597305, 2021). "Consistently, HNF4α-negative mesenchymal liver cancer cell lines have rewired SAA metabolism and are more resistant to cell death induced by methionine/cystine restriction or sorafenib than HNF4α-positive liver cancer cells." (PMID 32770044, 2020). "Although our study uncovers a key role of HNF4α in regulation of SAA metabolism, it does not exclude the involvement of other factors in this process, particularly in human liver cancer cell lines." (PMID 32770044, 2020). "Interestingly, we also observed an inverse correlation between HNF4α and PED mRNA expression in the non-tumoral liver tissues of the HCC patients, suggesting that PED regulation by HNF4α is not restricted to liver cancer cells." (PMID 29072691, 2017). "In addition, although miR-24 negatively regulates the expression of hepatocyte nuclear factor 4-alpha (HNF4-alpha) and thus might be up-regulated in some liver cancers, we did not observe this." (PMID 24130799, 2013).
colon carcinoma (48 papers, 2009 to 2025). "Mechanistically, DKK2 protein deficiency recovered protein levels of Hepatocyte Nuclear Factor 4 alpha (HNF4A) in colon cancer cells." (PMID 38659853, 2024). "Amongst the CDX2-correlated genes from human colon cancers, those downregulated in proximal organoids with Cdx2 loss included the key epithelial regulatory genes, such as Hnf4A, Satb2, and Vil1." (PMID 38360902, 2024). "The dysregulation of HNF4α expression has been linked with various human diseases like colon cancer, hepatocellular carcinoma, liver cirrhosis, ulcerative colitis, and maturity-onset diabetes of the young." (PMID 38372868, 2024). "But studies have illustrated, in small intestine and colon cancer, loss of HNF4α activated the WNT/β-catenin signaling pathway." (PMID 30405404, 2018). "Dysregulation of the HNF4A gene is linked to several gastrointestinal disorders including colitis and colon cancer and a single nucleotide polymorphism in the HNF4A gene region is associated with ulcerative colitis." (PMID 27166517, 2016). "HNF4α has been implicated in colitis and colon cancer in humans but the role of the different HNF4α isoforms expressed from the two different promoters (P1 and P2) active in the colon is not clear." (PMID 27166517, 2016). "Certain individuals with SNP variants of HNF4A may be more susceptible to Src kinase-mediated colon cancer." (PMID 37635981, 2023). "Furthermore, previous research has demonstrated that HNF4A isoforms showed significant metabolic differences and varied susceptibilities to colitis-associated colon cancer in exon-swap mice." (PMID 33710810, 2021). "HNF4a, down regulated by PL + CO in the duodenum, binds LA and plays a critical role in maintaining intestinal health, intestinal epithelial differentiation and barrier function 62–64; it is also dysregulated in colon cancer as well as colitis and is an IBD susceptibility gene 4,65,66." (PMID 37886485, 2023). "A subset of colon cancer cell lines displayed increased HNF4α expression, and immunohistochemical analysis revealed the upregulation of HNF4A expression during the process of carcinogenesis relative to normal and precancerous lesions." (PMID 40277924, 2025). "HNF4α and p-S133-CREB1 were significantly enriched at the promoter of Ctnnb1 in Apc mutation induced colon cancer tissues." (PMID 39320349, 2024). "In line with this, IPA of the bulk RNA-seq data using mouse colon cancer organoids suggested that HNF4A is activated in KO organoids." (PMID 38659853, 2024). "Taken together, DKK2-mediated reduction of HNF4A protein promotes the generation of lysozyme positive cancer cells with Paneth cell properties in the metastasized colon cancers." (PMID 38659853, 2024). "In a recent study, two HNF4α promoters were identified (P1 and P2), each of which expresses HNF4α transcriptional variants that are differentially expressed in human HCC and colon cancer." (PMID 35053606, 2022). "FOXA2 was previously implicated in cell proliferation, cancer stem cell maintenance, and an increase in relapse in triple-negative breast cancer, while HNF4A was related to an increase in lymph node and distant metastasis in colon cancer." (PMID 35205397, 2022). "Aberrations in the HNF4α signaling pathway have been reported in many GIT cancers including colon cancer, gastric cancer, and pancreatic cancer." (PMID 34771521, 2021). "Nevertheless, most of these reports with respect to the role of HNF4α in colon cancer are still unclear." (PMID 34771521, 2021). "HNF4A as a tumor suppressor in liver and colon cancers, its gene is silenced in the squamous subtype of pancreatic ductal adenocarcinoma." (PMID 34595169, 2021). "HNF4α is a highly conserved transcription factor that plays a role as a tumor suppressor gene or an oncogene in colon cancer." (PMID 33058307, 2021). "In contrast, P2-driven HNF4A is induced in colon cancer though combined actions of Paired Box 6 (PAX6) and HNF1A." (PMID 32998360, 2020).
colon carcinoma (continued). "The inverse correlation between HOTAIR and HNF4α expression was confirmed in colon cancer cells, with HOTAIR upregulation in EMT-like SW480 cells, expressing low levels of HNF4α, and HOTAIR downregulation in MET-like HNF4α-positive SW620 cells." (PMID 30154449, 2019). "One target gene of HNF4A is galectin 4, which was described as tumor-suppressor in colon cancer, but also pancreatic duct adenocarcinoma, and was accordingly positively associated with high CDX1 mRNA expression in the current study." (PMID 30909444, 2019). "In contrast, the HNF4A gene and protein are amplified in human colon cancer although the different isoforms were not distinguished in those studies." (PMID 27166517, 2016). "We further attempted to evaluate the effects of HNF4α regulation on colonic cancer cell lines." (PMID 40277924, 2025). "HNF4A mediates the formation of Lysozyme positive colon cancer cells by DKK2." (PMID 38659853, 2024). "Expression of HNF4α in the intestines and colon is relevant given that HNF4A is an IBD susceptibility gene and P1-HNF4α (but not P2-HNF4α) is a target of Src tyrosine kinase in human colon cancer." (PMID 37600688, 2023). "In human colon tumors, P1-driven HNF4A is either lost or localized in the cytoplasm due to an isoform-specific phosphorylation of HNF4A by SRC tyrosine kinase affecting protein stability, nuclear localization, and transactivation function of P1-driven, but not P2-driven, isoforms." (PMID 32998360, 2020). "While a loss of P1- but not P2-HNF4α has been noted in colon cancer, the specific roles of the HNF4α isoforms remain obscure." (PMID 27166517, 2016). "Moreover, it was shown that the inactivation of HNF4α in colon cancer cells and conditionally knockout mice decreased the expression of the gut-specific homeotic TF Cdx2, suggesting their positive correlation and tumor suppressive activity of HNF4α in colon cancer." (PMID 38372868, 2024). "Moreover, relatively high co-expression scores were also observed for RUNX2/ETS1, RUNX2/FOXO3, HNF1B/HNF4A, and HNF1B/FOXA3, suggesting that the DETFs associated with DARs might work together and be responsible for 5-FU resistance in colon cancer cells." (PMID 35252200, 2022). "Similarly, both promoters of HNF4A were significantly hypo-methylated in liver and colon cancers." (PMID 27016420, 2016). "LINC00858 reportedly regulates HNF4α and WNK2 to produce a tumor-promoting function in colon cancer." (PMID 35468892, 2022). "The expression of HNF4α is controlled by epigenetic mechanisms and siRNA-mediated silencing of HDAC3 and 4 reduces its expression as well as target gene transcription in colon carcinoma cells." (PMID 32982982, 2020). "Here, the HNF4α repressive activity is extended to HOTAIR transcription both in hepatocytes and colon cancer cells." (PMID 30154449, 2019). "While HOTAIR expression is stably down-regulated by HNF4α in several models of epithelial cells, including hepatocytes, its expression is reactivated during EMT/MET and in hepatocyte-specific Hnf4a knockout mice and colon cancer cells." (PMID 41595461, 2025). "Expression profiling in HCT116 colon cancer cells revealed ligand occupancy does not impact the transactivation potential of HNF4α; in fact the presence of a ligand modestly represses HNF4α activity." (PMID 37635981, 2023). "Data from the Achilles project established that HNF4α shRNA knockdown has a negative effect on proliferation and viability of colon cancer cells." (PMID 34771521, 2021). "Accordingly, P1-derived HNF4A acts as a tumor suppressor in a colon cancer xenograft model, while P2-derived HNF4A does not." (PMID 32998360, 2020). "HNF4α, a master factor of MET and inducer of epithelial differentiation, was found to directly repress HOTAIR transcription thus antagonizing the EMT of both hepatocytes and colon cancer cells." (PMID 30154449, 2019).